RFX8 (regulatory factor X8)
Description:
May be a transcription factor.
Synonyms: FLJ42986
Tractability: No criterion of Open Targets' tractability assessment is met for any kind of drug.
Gene: Protein-coding gene on chromosome 2 (101,397,359 to 101,475,112, reverse strand). Ensembl gene ENSG00000196460.
Subcellular location: Nucleus
Subcellular location (Human Protein Atlas): Nucleoplasm; Nuclear bodies
Gene Ontology:
Molecular function: DNA-binding transcription factor activity, RNA polymerase II-specific; RNA polymerase II cis-regulatory region sequence-specific DNA binding; DNA binding; DNA-binding transcription factor activity
Biological process: regulation of transcription by RNA polymerase II; regulation of DNA-templated transcription
Cellular component: chromatin; nucleus
Genetic constraint (gnomAD): Loss-of-function variants: 25 observed, 31.45 expected, observed/expected ratio (o/e) 0.79, 90% interval 0.58 to 1.11. The upper end of that interval is the gene's LOEUF score, 1.11, which puts it in group 4 of 6, group 1 being the genes least tolerant of losing a copy. Missense variants: 361 observed, 372.27 expected, observed/expected ratio (o/e) 0.97, 90% interval 0.89 to 1.06. Synonymous variants: 131 observed, 139.23 expected, observed/expected ratio (o/e) 0.94, 90% interval 0.82 to 1.09.
Homologues: Orthologues: chimpanzee RFX8 (95% identical), macaque RFX8 (90% identical), rabbit RFX8 (78% identical), dog RFX8 (77% identical), pig RFX8 (74% identical), rat Rfx8 (74% identical), mouse Rfx8 (72% identical), guinea pig RFX8 (68% identical), Caenorhabditis elegans daf-19 (16% identical). Paralogues in human: RFX6 (21% identical), RFX2 (20% identical), RFX1 (19% identical), RFX3 (19% identical), RFX4 (19% identical), RFX7 (13% identical), RFX5 (6% identical).
Diseases named in the same sentence as RFX8 in open-access papers:
RFX8 is named in the same sentence as 7 diseases in open-access papers, as found by Europe PMC text mining. Sharing a sentence is not in itself a finding about the gene and the disease. The quoted sentences say what the papers report.
schwannoma (2 papers, 2018 to 2021). A benign, usually encapsulated slow growing tumor composed of Schwann cells. "RFX8 was most prominently expressed in Schwannoma cells, suggesting a role for RFX8 in Schwann cell proliferation." (PMID 29510665, 2018). "It was suggested that RFX8 could play roles in Schwann cell proliferation, as it was detected to be most prominently expressed in the schwannoma cell line." (PMID 34368281, 2021). "In primary cells and cell lines, RFX8 TSS locations had higher expression values, with the most prominent expression in a Schwannoma cell line." (PMID 29510665, 2018).
myeloma (1 paper, 2023). "We selected genes (ARHGAP26, MYH10, PMP2, RFX8, BAMBI, CLEC12b) with significant changes in methylation level to validate their expression using qRT-PCR in U266 myeloma cells." (PMID 38201971, 2023).
neurodevelopmental disorder (1 paper, 2021). A behavioral and cognitive disorder with onset during the developmental period that involves impaired or aberrant development of intellectual, motor, or social functions. "Meanwhile, RFX8 has been identified as a candidate gene underlying human neurodevelopmental disorders." (PMID 34368281, 2021).
RFX8 also shares sentences with these, for which no sentence is quoted: cancer (1 paper); Infertility (1); mental disorder (1); Obesity (1).